STAT3 (signal transducer and activator of transcription 3)
Diseases named in the same sentence as STAT3 in open-access papers (continued):
Sharing a sentence is not in itself a finding about the gene and the disease.
tumor (continued). "In xenograft tumour models, reducing CD96 levels can accelerate mitochondrial fatty acid β‐oxidation by regulating the Src‐Stat3‐Opa1 signalling axis, thereby enhancing the resistance of breast CSCs to chemotherapy." (PMID 40665579, 2025). "Given our prior findings implicating CMSP in the regulation of the JAK2/STAT3/c-Myc axis, we further focused on MYC as a potential effector mediating the anti-tumor effects of CMSP." (PMID 41347093, 2025). "In macrophages, the M2 phenotype can promote tumor development, while FOSL1 can prevent macrophages from differentiating into the M2 phenotype by activating the STAT3 pathway and other downstream pathways." (PMID 40821785, 2025). "In particular, the STAT3 signaling pathway, which is considered a major pathway of cancer inflammation, interacts with the PI3K-AKT pathway to regulate tumor cell growth and survival." (PMID 40872503, 2025). "Ectopically expressed DDX5 facilitated transcription factor STAT3 activation by resolving the RNA G-quadruplex structure of STAT3, resulting in a higher level of CXCL11 transcription and an increase in tumor-infiltrating CD8+ T cells." (PMID 40651961, 2025). "The effects are supported by the compound's ability to regulate a variety of oncogenic and tumor‐suppressive signaling pathways, particularly PI3K/Akt, STAT3, NF‐kB, MAPK, AMPK, and Wnt/beta‐catenin." (PMID 41164269, 2025). "In triple-negative breast cancer, tumor- and stroma-derived vesicles can activate the HDAC6/STAT3/PD-L1 signaling cascade, facilitating immune evasion." (PMID 41228309, 2025). "Inhibition of the IL-6 downstream JAK/STAT3 signaling pathway has been shown to effectively suppress HCC cell proliferation and tumor growth." (PMID 40969371, 2025). "Platinum based drugs temporarily upregulate PD-L1 expression in tumor cells by activating DNA damage response pathways (such as ATM/ATR) and their downstream STAT3/NF - κ B signaling." (PMID 41293424, 2025). "This study highlights that dysregulated NF-κB and STAT3 signalling contributes to the observed inflammatory signature found in TSC cell line models and in TSC patient tumours." (PMID 41013689, 2025). "Firstly, in terms of promoting tumor cell proliferation, IL-6 binds to its receptor on cancer cells, activating the JAK/STAT3 signaling pathway." (PMID 39980561, 2025). "Overall, the tumor cells’ autonomously enhanced glycolysis and protein lactylation modification upregulate CCL2 expression through the ENSA-K63la/SRC-pS12/STAT3-pY705 axis, thereby recruiting macrophages." (PMID 39883522, 2025). "These cells are activated by factors such as TGF-β and SDF-1 secreted by tumor cells, transforming into CAFs with pro-tumorigenic properties via the TGF-β/Smad or the JAK/STAT3 signaling pathway." (PMID 40890855, 2025). "STAT3 is frequently hyperactivated in CRC and contributes to tumor proliferation, angiogenesis, invasion, immune evasion, and resistance to therapy." (PMID 41287778, 2025). "The IL6/IL6R/gp130 complex activates signaling pathways via STAT3 and MAPK activation, which not only drive angiogenesis but also contribute to tumor progression." (PMID 40427188, 2025). "Together, this study suggests that GSCs activate STAT3 to upregulate CYP3A5 to fine-tune NAD+/NADH for the enhancement of mitochondrial functions and DNA damage repair, thereby fueling tumor stemness and conferring TMZ resistance, respectively." (PMID 39754188, 2025). "Additionally, in its unphosphorylated form, where phenylalanine replaces tyrosine 705, STAT3 regulates NF‐κB transcription and genes associated with EMT by interacting with either unphosphorylated NF‐κB or Jun activation domain‐binding protein 1, contributing to tumor suppression." (PMID 40166646, 2025). "Chronic inflammation induced by MS activates signaling pathways such as NF-κB, STAT3, and PI3K/AKT, thereby augmenting the malignant phenotype of tumor cells." (PMID 41164182, 2025).
tumor (continued). "For example, STAT3 binds to the promoter region of the HOTAIR gene, enhancing its expression and thereby promoting EZH2‐mediated silencing of tumor suppressor genes in HNSCC." (PMID 40231344, 2025). "Mechanistically, it was discovered that IL-17 in plasma cells stimulates signal transducer and activator of transcription 3 (STAT3) signaling and activates eosinophils, thus boosting the pro-tumor environment." (PMID 41283232, 2025). "Meanwhile, Western blot confirmed the inhibitory effects of NCTD on p-STAT3 and p-JAK2 protein levels in tumor tissues." (PMID 40394236, 2025). "In vivo experiments confirmed that the co‐administration of IDET and paclitaxel significantly suppresses tumor growth in TNBC models, accompanied by a marked reduction in phosphorylated STAT3 and Bcl‐2 expression, while exhibiting favorable systemic tolerance." (PMID 40918170, 2025). "Computational prediction identified several tumor-suppressor genes, including PTEN, STAT3, RhoB, and PDCD4, as potential direct targets of miR-21-5p." (PMID 41465544, 2025). "Concurrently, SASP reprograms cancer metabolism; IL-6-induced STAT3 activation shifts energy production toward glycolysis while suppressing oxidative phosphorylation (OXPHOS), thereby fueling rapid tumor growth." (PMID 40510156, 2025). "SC-derived cytokines such as IL-6, TNF-α, and TGF-β play pivotal roles in promoting tumor cell proliferation, invasion, and perineural invasion (PNI) through activation of critical signaling pathways like STAT-3 and NF-κB." (PMID 40567365, 2025). "IDET modulates various molecular targets, including NF‐κB, PI3K/AKT/mTOR, Wnt/β‐catenin, STAT3, and MAPK, thereby influencing processes such as apoptosis, autophagy, cell cycle regulation, and cell survival, which in turn affect tumor progression." (PMID 41394539, 2025). "TANs preferentially create OSM (oncostatin M), and TAMs preferentially express IL-11, which promotes STAT3 signaling in ICC cells and tumor development." (PMID 40422244, 2025). "Future experiments should address two possibilities: STAT3 activation is inhibited by TILs and CD8+ T cells, or STAT3 activation is primarily driven by intrinsic tumor-related mechanisms." (PMID 41104968, 2025). "DR6 is required for the angiogenesis of mouse B16 tumor via the NF-κB, P38 MAPK, and STAT3 pathways." (PMID 38478147, 2025). "Further validation showed that overexpressed IL-11 inhibits CD8 + T cell proliferation and promotes tumor development via the Janus kinase 2/signal transducer and activator of transcription 3 (JAK2/STAT3) pathway." (PMID 40057816, 2025). "In contrast, the STAT3 inhibitor SH4-54 alone, which was more effective in combination with anakinra, significantly inhibited tumor progression." (PMID 41436606, 2025). "Concurrently, C3 cleavage fragments stimulate the JAK2/STAT3 and ERK pathways, driving cellular reprogramming that promotes tumor progression." (PMID 40370471, 2025). "TGF-β is also a key driver of EMT, facilitating tumor initiation, invasion and metastasis by regulating multiple signaling pathways, including MAPK/ERK1/2, NF-κB/Snail, JAK/STAT3 and PI3K/AKT signaling." (PMID 40805201, 2025). "The WB test results revealed that the expression levels of JAK/STAT3/CCL-2 pathway-related proteins p-JAK/JAK, p-STAT3/STAT3 and CCL-2 were significantly cut down in the tumor cells of the sh-OSMR group relative to the sh-NC group." (PMID 40161370, 2025). "Its phenolic structure facilitates free radical scavenging and inflammation modulation while inhibiting tumor growth via PI3K/Akt and STAT3 signaling pathway regulation." (PMID 41149645, 2025). "With regards to altered immune regulation in tumor microenvironment, TAM-derived IL-6 promotes signal transducer and activator of transcription 3 (STAT3) phosphorylation, leading to decreased apoptosis in tumor cells." (PMID 39996747, 2025).
tumor (continued). "In vitro, STA has been found to impede tumor cell migration, invasion, and angiogenesis by preventing TAMs from polarizing to the M2 phenotype via the JAK2/STAT3 signaling pathway." (PMID 39974738, 2025). "Here, we show that STAT3 inhibition by WP1066 induced cell apoptosis and reduced tumor cell proliferation in vitro." (PMID 40529368, 2025). "STAT3 inhibition led to significantly reduced proliferation of tumor-educated THP1 cells, emphasizing the critical role of STAT3 signaling in mediating cancer-induced immune activation." (PMID 41514627, 2025). "TUBA1B expression also positively correlated with immune-related pathways like interferon-alpha/gamma response, IL-2/STAT5 signaling, and IL6/JAK/STAT3 signaling, indicating TUBA1B’s significant role in the tumor immune microenvironment (TIME)." (PMID 39968182, 2025). "In contrast, in pancreatic, colon or glioblastoma tumors, CXCL10 can activate alternative signaling pathways such as STAT3, which promotes immunosuppression, or PI3K/Akt, which supports tumor cell proliferation and resistance to apoptosis." (PMID 40760734, 2025). "The released IL-10 activated the STAT1/STAT3 signaling pathway to alleviate CAP-induced endoplasmic reticulum stress in tumor cells, finally resulting in attenuation of programmed death of tumor cells after CAP exposure." (PMID 41145470, 2025). "This reduction promotes the activation of nuclear factor kappa-light-chain-enhancer of activated B cells (NF-κB) and signal transducer and activator of transcription 3 (STAT3) signaling pathways, ultimately promoting enhanced tumor growth and metastasis." (PMID 40356596, 2025). "STAT3 is the main downstream regulator of IL6 signal transduction and plays a unique role in regulating inflammation and tumor transformation." (PMID 40841364, 2025). "Collectively, BSS and Lut regulate tumor proliferation, immune evasion, and inflammatory microenvironments by targeting Wnt/β-catenin, MAPK, PI3K/AKT, and STAT3 pathways." (PMID 41479912, 2025). "Partial Dhcr7 deletion produced the most profound effect on tumorigenesis in DEN/HFD + EtOH-fed Dhcr7+/– mice, as shown by reduced tumor number, diameter, and expression of AFP and YAP, and phospho-STAT3." (PMID 40529212, 2025). "Signals from the tumor microenvironment, such as reduced TGF-β signaling, activation of NF-κB and STAT3 pathways, or stimulation by oncostatin M from tumor-associated macrophages and neutrophils, strongly upregulate CXCL1 expression in iCAFs." (PMID 40940809, 2025). "Moreover, we confirmed that MAML1 could drive HCC tumour growth in vivo, which could be blocked by the inhibition of STAT3 signaling either by ruxolitinib administration or shRNA, suggesting that the tumour-promoting role of MAML1 is dependent on STAT3 signaling." (PMID 41345959, 2025). "While LIF promotes tumor proliferation, chemoresistance, and immune suppression via JAK/STAT3, MAPK/ERK, and Hippo‐YAP signaling, its context‐dependent tumor‐suppressive roles add layers of complexity." (PMID 41163398, 2025). "In neutrophils, STAT3 and STAT5 are the primary transcription factors mediating tumor-promoting effects." (PMID 40486614, 2025). "Previous studies have established that the expression of CD274/PD-L1 was associated with multiple signaling pathways, including IL-6/JAK/STAT3, PI-3K/AKT/mTOR, JAK/STAT, and WNT, which collectively influenced the tumor immune microenvironment." (PMID 40953006, 2025). "The overexpression of HMGA2 in CRC cells promoted macrophage recruitment and M2 polarization by upregulating STAT3-mediated CCL2 secretion, thereby promoting tumor immune suppression in CRC." (PMID 40703517, 2025). "CUR affects the STAT3 pathway in mice by significantly inhibiting tumor growth and downregulating the expression of p‐STAT3 and p‐JAK2 in tumor samples." (PMID 40860906, 2025).
tumor (continued). "Recent studies in mouse tumor models have shown that LPS promotes angiogenesis within tumor tissues by modulating the EGFR/IL8 and VEGFR/STAT3 signaling pathways, thereby enhancing tumor growth, proliferation, and metastasis." (PMID 40458800, 2025). "To further translate these findings to human settings, we blocked STAT3 signaling in cancer patient neutrophils via the small molecule inhibitor LLL12 and assessed its effects on patient-derived tumor explants." (PMID 40885734, 2025). "Disruption of the STAT3 pathway impedes tumor progression and suppresses the secretion of soluble factors by SCC tumor cells." (PMID 40399946, 2025). "For example, leptin produced by adipocytes upregulates enzymes involved in FAO by activating the transcription factor STAT3, which inhibits the glycolysis of CD8+T effector cells and impair their anti-tumor effects." (PMID 40290117, 2025). "For example, STAT1 and STAT3 generally mediate opposite roles, with STAT1 acting as a tumor growth suppressor based on its role as a pro-apoptotic and anti-proliferative molecule, while STAT3 is considered an oncogenic TF." (PMID 39942749, 2025). "CXCL8 was also found to be significantly upregulated in HCC, promoting tumor progression and metastasis through activation of the AKT/mammalian rapamycin target protein (mTOR)/STAT3 pathway." (PMID 40145607, 2025). "In any case, further studies of KMT2A/MLL1, DOT1L and STAT3 dependency across a range of ETS-driven mouse and human tumor models are warranted, particularly with the potential for near-term translational impact using existing clinical-grade inhibitors." (PMID 40858905, 2025). "Our data show that the CD3- and CD20-negative tumor formations resembled characteristic features of NHL and histopathologically exhibited immunopositivity for both tyrosine-phosphorylated STAT1 and STAT3." (PMID 40287766, 2025). "METTL3 further mediates m6A modification of JAK1 mRNA, and the m6A-YTHDF1 axis ultimately promotes JAK1 protein translation and STAT3 phosphorylation, facilitating CRC immune evasion and tumor progression." (PMID 39897556, 2025). "Specifically, it has been demonstrated that ginsenoside Rg3 regulates STAT3 and suppresses the secretion of CCL2 by tumor cells." (PMID 40490812, 2025). "In the Tumor–Myeloid interaction, enrichment was observed in immune-related pathways such as ‘IL-6/JAK/STAT3 Signaling’, ‘Cytokine–cytokine receptor interaction’, ‘Inflammatory Response’, and ‘Chemokine binding’." (PMID 40806243, 2025). "The JAK2/STAT3 signaling pathway is critical in angiogenesis-related disorders, with STAT3-dependent VEGF expression reported in human tumor cells." (PMID 40426248, 2025). "On the one hand, nuclear PKM2 upregulates PD-L1 expression through STAT3 phosphorylation and remodels chromatin accessibility via HDAC3 recruitment, contributing to immunosuppressive tumor microenvironments." (PMID 40842995, 2025). "Tumor cells subvert neighboring B cells through IL-6/STAT3 signaling and CD40L-mediated activation, reprogramming them into pro-tumor effectors that secrete survival factors." (PMID 41246318, 2025). "In MDA-MB-231 breast cancer cells, morin suppresses the EGFR/STAT3 pathway due to the suppression of FOXM1 and chemosensitization of tumor cells." (PMID 39966334, 2025). "It is reported that the abnormally activated JAK2/STAT3 signaling pathway enhances the occurrence and development of HCC by promoting tumor cell proliferation, migration, invasion, angiogenesis, and apoptosis inhibition." (PMID 41200213, 2025). "Immune alterations also include increased CD4 +/CD8 + and IL-17 + γδ T cells, and elevated expression of immunosuppressive (IDO1, IL-10, PD-L1) and oncogenic (AKT1, STAT3, CXCR4) genes with key roles in tumor progression and immune evasion." (PMID 40924302, 2025). "As critical pro-carcinogenic mediators, NF-κB and STAT3 suppress STAT1 and NF-κB-dependent immune responses, thereby undermining anti-tumor immunity." (PMID 40420174, 2025).
tumor (continued). "Meanwhile, deficiency of circRNA-14,052 led to a significant decrease in circRNA-14,052, IKBKB, IL-6, JAK2, and STAT3 levels, and an increase in miR-214-3p levels in tumor tissues from MCF-7 tumor-bearing mice compared to the LV-NC group." (PMID 41044672, 2025). "Tumor cells have been shown to produce high levels of PD-L1, downregulate costimulatory molecules and MHC, express/activate STAT3, eliminate PTEN, lower immunogenicity, and attract Tregs." (PMID 40504869, 2025). "In cancer development and progression, IL-6 can promote tumor cell proliferation, anti-apoptosis and angiogenesis by activating JAK/STAT3 and other signaling pathways." (PMID 41376630, 2025). "Another STAT3 inhibitor, WP1066, has demonstrated effectiveness in reducing tumor invasiveness and improving immune response, making it promising for reducing tumor spread." (PMID 40735045, 2025). "It further drives tumor growth and reduces sorafenib sensitivity by upregulating HIF-1α and activating JAK2/STAT3 signaling." (PMID 41050691, 2025). "Disrupting astrocyte–tumor cell interactions, targeting key signaling pathways such as STAT3, CHI3L1, and PPAR-gamma, and developing microRNA-based therapies are promising strategies for inhibiting astrocyte-mediated tumor progression." (PMID 39858080, 2025). "The results indicated a positive correlation between the expression of STAT3 and FN1 with angiogenesis, tumor inflammation, and epithelial-mesenchymal transition (EMT)." (PMID 40772037, 2025). "By directly upregulating B7-H4 via STAT3 signaling, SOX9 reduces CD8+ T cell infiltration while increasing Tregs, effectively shutting down anti-tumor immunity." (PMID 41293317, 2025). "For instance, STAT3, IL6, and TNF are key inflammatory mediators that activate downstream NF-κB signaling and support a tumor-permissive microenvironment." (PMID 40593037, 2025). "STAT3 inhibitors like TTI-101 and SH5–07 have shown efficacy in reducing tumor proliferation and enhancing cell death, potentially augmenting responses to existing therapies." (PMID 40735045, 2025). "Both in vitro and in vivo studies support its capacity to inhibit tumor growth, activate caspases, and modulate critical signaling pathways such as PI3K/Akt and STAT3." (PMID 41155573, 2025). "Our data showed that KDM6B overexpression significantly increased phosphorylated STAT3 levels in CRC cells and tumor tissues compared with the control group." (PMID 40959109, 2025). "STAT3 is constitutively activated in PDAC cell lines, PDAC xenografts, and primary human PDAC, playing a role in tumor development and EMT activation." (PMID 40001578, 2025). "Specific examples, such as curcumin, have been shown to enhance anti-tumor immunity in CAT by elevating CD8+ T cell function and downregulating the AKT/mTORC1/STAT3/PD-L1 axis." (PMID 40943396, 2025). "Under hypoxic condition in tumor sites, the upregulation of CD45 tyrosine phosphatase activity in MDSCs is needed to mediate the downregulation of STAT3 in a HIF-1α-independent manner." (PMID 40380196, 2025). "Specifically, IL-11 activates STAT3 phosphorylation, which inhibits IFNγ-induced STAT1 phosphorylation, thereby downregulating MHC-I and CXCL9 expression in tumor cells and impairing CD8+ T cell infiltration—promoting immune evasion and tumor growth in CRC." (PMID 41359051, 2025). "IL-8, for example, has been shown to activate fibroblasts via STAT3 phosphorylation, upregulating MMP1 and promoting tumor cell invasion." (PMID 40472740, 2025). "Curcumin reduced phosphorylation of STAT3 by downregulating IL6 expression, thereby diminishing the proliferation and anti-apoptotic capabilities of tumor." (PMID 40535567, 2025). "Tumor‐produced GM‐CSF activates neutrophils and promotes PD‐L1 expression through the JAK/STAT3 signaling pathway." (PMID 40979214, 2025).